STAP2 (signal transducing adaptor family member 2)
Description:
Substrate of protein kinase PTK6. May play a regulatory role in the acute-phase response in systemic inflammation and may modulate STAT3 activity.
Synonyms: STAP-2; BKS
Tractability: Antibody: its Gene Ontology location is reachable by antibodies, with high confidence. PROTAC: ubiquitination databases record sites on it; its protein half-life has been measured.
Gene: Protein-coding gene on chromosome 19 (4,324,040 to 4,342,786, reverse strand). Ensembl gene ENSG00000178078.
Subcellular location: Cytoplasm
Pathways (Reactome):
Cellular responses to stimuli: Cytoprotection by HMOX1
Signal Transduction: PTK6 Activates STAT3
Gene Ontology:
Molecular function: protein binding; signaling adaptor activity
Cellular component: cytosol; plasma membrane; cytoplasm
Genetic constraint (gnomAD): Loss-of-function variants: 58 observed, 53.75 expected, observed/expected ratio (o/e) 1.08, 90% interval 0.87 to 1.34. The upper end of that interval is the gene's LOEUF score, 1.34, which puts it in group 5 of 6, group 1 being the genes least tolerant of losing a copy. Missense variants: 522 observed, 523.54 expected, observed/expected ratio (o/e) 1, 90% interval 0.93 to 1.07. Synonymous variants: 231 observed, 212.76 expected, observed/expected ratio (o/e) 1.09, 90% interval 0.97 to 1.21.
Homologues: Orthologues: chimpanzee STAP2 (99% identical), macaque STAP2 (89% identical), pig STAP2 (80% identical), dog STAP2 (72% identical), rat Stap2 (71% identical), mouse Stap2 (70% identical), guinea pig STAP2 (63% identical), zebrafish stap2a (36% identical), tropical clawed frog stap2 (31% identical), zebrafish stap2b (31% identical). Paralogues in human: STAP1 (23% identical).
Diseases named in the same sentence as STAP2 in open-access papers:
STAP2 is named in the same sentence as 24 diseases in open-access papers, as found by Europe PMC text mining. Sharing a sentence is not in itself a finding about the gene and the disease. The quoted sentences say what the papers report.
prostate carcinoma (7 papers, 2018 to 2024). A carcinoma that arises from epithelial cells of the prostate gland. "EGF-induced Ub of EGFR increased in STAP-2-deficient cells but decreased in STAP-2-overexpressing prostate cancer DU145 cells." (PMID 38745775, 2024). "In particular, prostate cancer cells express STAP-2 at high levels, similar to those in breast cancer cells." (PMID 38745775, 2024). "In prostate cancer cells, STAP-2 interacts with and stabilizes epidermal growth factor receptor (EGFR) after stimulation, resulting in the upregulation of EGFR signaling, which contributes to cancer-cell proliferation and tumor progression." (PMID 38745775, 2024). "STAP2 is a signal-transducing adaptor protein 2 that promotes prostate cancer growth by enhancing EGFR stabilization." (PMID 36555586, 2022). "Another biological mechanism of STAP-2 in prostate cancer cells is to inhibit the CBL-enhanced ubiquitination of EGFR and to restore EGFR." (PMID 36010693, 2022). "STAP2 is known to increase cell growth and tumor progression in breast and prostate cancer by interacting with the Brk and STAT pathways." (PMID 30555413, 2018). "STAP-2 enhances EGFR-mediated proliferation of DU145 human prostate cancer cells." (PMID 36410436, 2022). "A knockdown of STAP-2 inhibits the cell growth of prostate cancer cells." (PMID 36010693, 2022). "STAP-2 is also a potent regulator of EGFR activation in prostate cancer cells." (PMID 36010693, 2022). "A knockdown of STAP-2 may inhibit prostate cancer cell growth by synergistically inhibiting EGFR and IL6R signaling." (PMID 36010693, 2022). "Another SH2-containing protein involved in prostate cancer is the STAP-2 protein." (PMID 36555586, 2022). "Therefore, STAP-2 inhibitors may have the potential to be effective anticancer agents against gefitinib-resistant prostate cancer." (PMID 36010693, 2022). "STAP-2 increases EGFR phosphorylation in response to EGF and upregulates EGFR signaling in the prostate cancer cell line DU145." (PMID 38461189, 2024). "STAP-2 upregulates EGFR-mediated signaling, enhancing STAT3 activity in DU145 prostate cancer cells." (PMID 38745775, 2024). "STAP2 is an adaptor protein and commonly promotes tumorigenesis in melanoma, CML, breast and prostate cancer." (PMID 35565213, 2022). "Similar to PD-1/PD-L1, development of optimized peptides to inhibit the interactions between STAP-2 and EGFR is likely to have applications in the treatment of EGFR-related malignancies such as lung and prostate cancers." (PMID 36410436, 2022). "STAP-2 enhances signaling via EGFR through its protein stabilization, leading to higher tumorigenesis in prostate cancer cells." (PMID 36010693, 2022). "We previously demonstrated that STAP-2 binds to epidermal growth factor receptor (EGFR) and facilitates its stability and activation of EGFR signaling in prostate cancer cells." (PMID 36410436, 2022). "Several SH2-containing proteins are involved in the development of certain types of cancers, such as breast cancer (Grb2, Grb7, STAT3, and Src), liver cancer (STAT3), Prostate cancer (STAT3, STAP2), Chronic Myelogenous Leukemia, CML (Bcl/Abl)." (PMID 36555586, 2022). "STAP-2 knockdown negatively regulates the proliferation of DU145 and LNCaP prostate cancer cells." (PMID 38745775, 2024). "Notably, gefitinib treatment fails to further inhibit the cell proliferation of STAP-2-silenced prostate cancer cells." (PMID 36010693, 2022).
breast carcinoma (5 papers, 2018 to 2024). "STAP-2/BRK expression is deregulated in breast cancers and enhances STAT3-dependent cell proliferation." (PMID 38745775, 2024). "STAP-2 is also involved in the growth of breast cancer cells through its interaction with Brk and STAT3." (PMID 36551835, 2022). "Ikeda and colleagues showed that BRK and STAP-2 are highly expressed in breast cancer cells and reported that STAP-2 is phosphorylated at tyrosine-250 by BRK, thus enhancing BRK-mediated STAT3 activation." (PMID 29914167, 2018). "Moreover, STAP-2 promotes the proliferation and metastasis of various cancer cell lines such as melanoma, breast cancer, and chronic myeloid leukemia." (PMID 36410436, 2022). "As both BRK and STAP-2 expression are high in breast cancer cells, their coupling may promote the abnormal activation of STAT3." (PMID 36010693, 2022). "Indeed, silencing of endogenous STAP-2 expression by siRNA strongly reduced BRK-mediated STAT3 activation in T47D breast cancer cells." (PMID 29914167, 2018). "Thus, STAP-2 functions in concert with BRK to promote breast cancer cell proliferation." (PMID 36010693, 2022). "STAP-2 also binds to breast tumor kinase (BRK) and STAT3, resulting in the enhanced growth of T47D breast cancer cells." (PMID 38745775, 2024). "Altogether, these observations highlight the crucial role of STAP-2 in BRK-mediated STAT3 activation and tumor cell growth and propose this molecule as a potential therapeutic target and prognostic factor for breast cancer patients." (PMID 29914167, 2018). "Therefore, these “EGFR stabilizers”, including STAP-2, are good targets for the treatment of EGFR-overactivated cancers such as nonsmall cell lung, prostate, and breast cancers." (PMID 36410436, 2022). "For example, STAP-2 interacts with STAT5 through its PH domain after the Brk-mediated phosphorylation of STAP-2 in breast cancer cell lines, and this interaction may be important for the regulation of breast cancer cell growth." (PMID 36551835, 2022).
chronic myeloid leukemia (3 papers, 2020 to 2024). "In chronic myeloid leukemia cells, the interaction between STAP-2 and BCR-ABL is crucial in conferring growth advantages, resistance to imatinib (a BCR-ABL inhibitor), and tumor progression." (PMID 38745775, 2024). "In chronic myeloid leukemia cells, STAP-2 interacts with the fused BCR-ABL complex, resulting in the augmentation of its downstream signals." (PMID 38745775, 2024). "We previously cloned STAP-2 as a c-Fms interacting protein and explored its effects on chronic myeloid leukemia (CML) leukemogenesis." (PMID 32661325, 2020).
melanoma (2 papers, 2022 to 2024). A malignant, usually aggressive tumor composed of atypical, neoplastic melanocytes. "STAP-2 is also highly expressed in various cancer cells, including breast, prostate, lung cancer, melanoma, and leukemia." (PMID 38745775, 2024). "In B16-F10 melanoma cells, STAP-2 positively regulates tyrosinase protein levels and modulates tumor invasion by regulating chemokine receptor expression." (PMID 38745775, 2024).
Allergy (1 paper, 2017). An allergy is an immune response or reaction to substances that are usually not harmful. "Taken together, STAP2 acts as a key intracellular molecule in the process of the memory T cell differentiation probably including tissue residential memory T cells, which have received extensive attention in the medical areas of allergy, autoimmune disorders, infectious diseases, and cancer." (PMID 28430604, 2017).
autoimmune disease (1 paper, 2022). A disorder resulting from loss of function or tissue destruction of an organ or multiple organs, arising from humoral or cellular immune responses of the individual to their own tissue constituents. "STAP-2 in T cells contributes to Th17 generation and Th17-mediated autoimmune diseases." (PMID 36551835, 2022). "Therefore, STAP-2 expression may be involved in the development of T cell-dependent autoimmune diseases." (PMID 36551835, 2022). "We previously reported the critical function of STAP-2 in TCR-mediated T cell activation and T cell-mediated autoimmune diseases." (PMID 36551835, 2022).
fibrosarcoma (1 paper, 2017). A malignant mesenchymal fibroblastic neoplasm affecting the soft tissue and bone. "Subcutaneous CMS5a tumor cell (mERK2+ fibrosarcoma line [BALB/c background])-bearing BALB/c mice were infused with STAP2 siRNA- or scrambled siRNA-introduced DUC18 CD8+ T cells, and then subjected to in vitro or in vivo vaccination with mERK2 peptide or mERK2-encoded DNA." (PMID 28430604, 2017).
Granuloma (1 paper, 2022). A compact, organized collection of mature mononuclear phagocytes, which may be but is not necessarily accompanied by accessory features such as necrosis. "In contrast, lymphocyte-specific STAP-2 transgenic (Tg) mice showed severe splenomegaly and granuloma formation after the P. acnes treatment compared with WT mice." (PMID 36551835, 2022). "The granuloma area was significantly reduced in STAP-2 KO mice than in WT mice after the P. acnes injection." (PMID 36551835, 2022).
leukemia (1 paper, 2022). A malignant (clonal) hematologic disorder, involving hematopoietic stem cells and characterized by the presence of primitive or atypical myeloid or lymphoid cells in the bone marrow and the blood. "In this regard, STAP-2 may be a good target for treating patients with certain types of leukemia and solid tumors." (PMID 36551835, 2022). "Thus, STAP-2 is a good target for developing therapeutic medicines for patients with leukemia, especially CML." (PMID 36551835, 2022). "Thus, STAP-2 is likely to be a suitable target for the development of novel therapeutic drugs for patients with certain types of cancer, specifically leukemia." (PMID 36551835, 2022).
lung carcinoma (1 paper, 2022). "In conclusion, our study shows that 2D5 peptide is a novel anticancer peptide that inhibits STAP-2–mediated activation of EGFR signaling and suppresses prostate and lung cancer progression." (PMID 36410436, 2022).
sarcoma (1 paper, 2022). A usually aggressive malignant neoplasm of the soft tissue or bone. "Therefore, STAP2 potentially regulates signaling pathways, such as EGFR/PIK pathway, inducing sarcomas." (PMID 35565213, 2022).
tumor (8 papers, 2017 to 2024). "Despite the characteristic translocation t(x;18)(p11.2;q11.2), point mutations were identified, such as in signal-transducing adaptor family member-2 (STAP2), which correlated with the clinical course and tumor burden." (PMID 35565213, 2022). "In male lactotroph tumors, while we found STAP2 to be increased at all tumor grades, we noted that STAT3 and STAT5 were higher in male grade 2b/3 than in female grade 2b tumors." (PMID 30555413, 2018). "The optimized peptide 2D5 inhibited DU145 and A549 tumor growth similarly to STAP-2 knockdown." (PMID 36410436, 2022). "Notably, the EGFR/STAP-2 interaction is essential for sustaining EGFR expression on the surface of tumor cells by inhibiting the c-CBL-mediated ubiquitination of EGFR." (PMID 36551835, 2022). "STAP-2 knockdown in DU145 cells decreases their tumor formation in murine xenograft models." (PMID 36410436, 2022). "STAP-2 suppresses terminal effector CD8+ T cell generation, resulting in the promotion of tumor antigen-reactive memory CD8+ T cell development, although the detailed mechanism remains to be elucidated." (PMID 36551835, 2022). "In fact, attenuation of tumor growth was significantly observed in the scrambled siRNA-treated control group, but not the STAP2 siRNA-treated group." (PMID 28430604, 2017). "Moreover, STAP-2 knockdown-induced suppression of tumor cell growth was observed in EGFR-activated, but not in EGFR-inactivated states." (PMID 38745775, 2024).
cancer (4 papers, 2017 to 2024). A tumor composed of atypical neoplastic, often pleomorphic cells that invade other tissues. "Cytotoxicity of 2D5 peptide disappeared in STAP-2–knockdown DU145 cells, indicating that 2D5 peptide inhibited cancer cell growth dependently on STAP-2 expression." (PMID 36410436, 2022). "Among these cells, cancer cells express higher STAP-2 mRNA expression than normal cells." (PMID 38745775, 2024). "Therefore, STAP-2 inhibition can be developed as a therapeutic strategy for EGFR-related cancers." (PMID 38745775, 2024). "Therefore, inhibiting STAP-2 function may aid in developing anti-cancer drugs for various cancers." (PMID 38745775, 2024). "The fact that the STAP-2 PH and SH2 domains can bind to and modify several signaling molecules indicates that STAP-2 facilitates the initiation and progression of some cancer types." (PMID 38745775, 2024). "In this study, we showed that 2D5 peptide acted as an inhibitor of STAP-2–EGFR interactions and suppressed EGFR-mediated cancer cell growth." (PMID 36410436, 2022). "Here, we found that 2D5 peptide, a STAP-2–derived peptide, blocked STAP-2–EGFR interactions and suppressed EGFR-mediated proliferation in several cancer cell lines." (PMID 36410436, 2022). "Here, we found that a STAP-2 PH domain–derived peptide inhibited STAP-2–EGFR interaction and suppressed EGFR-mediated proliferation in several cancer cell lines." (PMID 36410436, 2022). "As STAP-2 is important for EGFR-mediated signaling, including the phosphorylation of EGFR, ERK, and STAT3 and proliferation of some human cancer-cell lines, we tested whether 2D5 suppresses these functions in a previous study." (PMID 38745775, 2024). "Indeed, the identified peptide inhibitor successfully suppressed the STAP-2/EGFR protein interaction, EGFR stabilization, and cancer-cell growth." (PMID 38745775, 2024). "2D5 peptide inhibited the proliferation of human, but not murine, cancer cells, suggesting that STAP-2 contributes to EGFR-mediated proliferation of human cancer cells, but not murine cancer cell lines." (PMID 36410436, 2022). "Therefore, inhibition of the interaction between STAP-2 and BRK/EGFR may be a possible therapeutic strategy for these cancers." (PMID 38745775, 2024). "Thus, we speculate that murine STAP-2 enhances EGFR-independent cell proliferation and does not affect EGFR signaling in murine cancer cells." (PMID 36410436, 2022).
immune diseases (2 papers, 2022 to 2025). "Here, we review how STAP-2 affects the pathogenesis of T cell-mediated inflammation and immune diseases in order to develop novel STAP-2-targeting therapeutic strategies." (PMID 36551835, 2022). "The manipulation of STAP-2 expression was shown to contribute to inflammatory and immune diseases and some malignancies critically." (PMID 36551835, 2022). "Thus, STAP-2 is a positive regulator of TCR signaling and may be a good therapeutic target for T cell-mediated immune disorders." (PMID 36551835, 2022).
infection (1 paper, 2024). The state of being infected such as from the introduction of a foreign agent such as serum, vaccine, antigenic substance or organism. "Since STAP-2 KO mice are viable and fertile without any reported abnormalities under steady-state conditions, it is thought that the functions of STAP-2 emerge in some abnormal situations, such as infection, inflammation, and tumorigenesis." (PMID 38461189, 2024).
STAP2 also shares sentences with these, for which no sentence is quoted: Autoimmunity (1 paper); bladder cancer (1); breast (1); ichthyosis (1); Immunodeficiency (1); infectious disease (1); multiple sclerosis (1); psoriasis (1); viral infections (1).